FDX1 (ferredoxin 1)
Diseases named in the same sentence as FDX1 in open-access papers (continued):
Sharing a sentence is not in itself a finding about the gene and the disease.
renal cell carcinoma (8 papers, 2022 to 2025). "The opposite result was found in renal cell carcinomas, where increased expression of FDX1 correlated with a better prognosis, demonstrating a different role of cuproptosis-inducing FDX1 in different tumor types." (PMID 39062119, 2024). "Decreased expression of FDX1 has been found in various tumor types such as renal cell carcinoma, and this decreased expression appears to be closely associated with poorer prognosis." (PMID 39062119, 2024). "Furthermore, a study reported adrenomedullin promotes resistance to sunitinib, through the reduction of FDX1 expression levels, thus inhibiting cuproptosis in renal cell carcinoma." (PMID 40547013, 2025). "In renal cell carcinoma, ADM is able to promote resistance to sunitinib, through the reduction of FDX1 expression levels, thus inhibiting cuproptosis." (PMID 39200990, 2024). "For instance, FDX1 expression was significantly positively correlated with differentiation and proliferation of AML and with stemness of renal cell carcinoma (RCC)." (PMID 36210836, 2022). "Additionally, adrenomedullin could reduce FDX1 transcription and suppress cuproptosis in renal cell carcinoma (RCC) through promoting p38/MAPK signaling pathway-mediated phosphorylation and nuclear translocation of Forkhead box O3 (FOXO3)." (PMID 38918694, 2024).
stomach adenocarcinoma (8 papers, 2022 to 2025). "This study underscores the importance of cuproptosis-related genes, particularly FDX1, in pathogenesis and prognosis of stomach adenocarcinoma." (PMID 40410601, 2025). "However, FDX1 expression in tumor tissues of Stomach adenocarcinoma (STAD) was higher than in normal tissues (p < .05)." (PMID 36755576, 2023).
lung squamous cell carcinoma (7 papers, 2022 to 2024). "Higher FDX1 expression is associated with better disease-free survival (DFS) and overall survival (OS) in renal cancer, liver hepatocellular carcinoma, LUAD, and lung squamous cell carcinoma." (PMID 38802900, 2024).
ovarian carcinoma (7 papers, 2018 to 2026). A malignant neoplasm originating from the surface ovarian epithelium. "In addition, knocking down FDX1 expression has been found to increase mitochondrial membrane potential loss and lipid peroxidation in ovarian cancer cells treated with cisplatin, thereby enhancing ferroptosis and increasing cisplatin sensitivity." (PMID 41505058, 2026). "This indicates that FDX1 normally inhibits cisplatin-induced ferroptosis in ovarian cancer cells, thereby promoting cisplatin resistance." (PMID 41505058, 2026). "No studies have yet reported the relationship between LRPPRC and cuproptosis, or its key molecule FDX1, in ovarian cancer." (PMID 41516324, 2025). "We then verified the expression of FDX1 in ovarian cancer cells at the transcription and protein levels." (PMID 36765541, 2023). "We explored the potential of YY1, FDX1, DLD, DLAT, and PDHB to serve as non-invasive diagnostic markers of ovarian cancer." (PMID 36484005, 2022). "Results indicated that FDX1 may contribute to cisplatin resistance in ovarian cancer cells by inhibiting the increase in mitochondrial membrane potential and cisplatin-induced lipid peroxidation." (PMID 40406488, 2025). "In addition, the expression levels of YY1 in the tissue samples from ovarian cancer patients were significantly positively correlated with the expression levels of FDX1, DLD, DLAT, PDHB, and other genes." (PMID 36484005, 2022). "Furthermore, it was found that inhibiting LRPPRC expression not only diminishes the translation of the core subunit MTCO1 of complex IV and the copper chaperone molecule SCO1 in A2780 and SKOV3 ovarian cancer cells, but also reduces the expression levels of FDX1 and LIAS." (PMID 41516324, 2025). "BACKGROUND: Ovarian cancer (OC) is often characterized by poor prognosis due to paclitaxel (TAX) resistance, with ferredoxin 1 (FDX1) emerging as a key mediator of copper metabolism." (PMID 42026685, 2026). "Developing small-molecule inhibitors of FDX1 could enhance copper accumulation in tumor cells, thereby promoting cuproptosis, particularly in malignancies that rely on mitochondrial respiration, such as certain ovarian cancers and clear cell renal cell carcinoma (ccRCC)." (PMID 40406488, 2025). "Bioinformatics analysis revealed that four core factors (lipoic acid pathway FDX1, DLD, DLAT, PDH), and transcription factor YY1 were highly expressed in ovarian cancer tissues and were significantly correlated with an unfavorable prognosis." (PMID 36484005, 2022). "The results of the cDNA expression profile analysis showed that four factors (i.e. FDX1, DLD, DLAT, PDHB) were highly expressed in the tumor tissues of ovarian cancer patients." (PMID 36484005, 2022). "We used an exosome database for screening and found that the levels of FDX1, DLD, DLAT, PDHB, and YY1 in peripheral blood exosomes from ovarian cancer patients were significantly higher than those in the normal controls." (PMID 36484005, 2022). "Knockdown of LRPPRC in ovarian cancer cells is believed to impact the assembly of complex IV by decreasing SCO1, while simultaneously affecting the biosynthesis of complex IV through the downregulation of FDX1 and lipoic acidylated proteins." (PMID 41516324, 2025). "Our study revealed that the expression of four core factors of the lipoic acid pathway (i.e., FDX1, DLD, DLAT, and PDHB) was distinct between ovarian cancer patients and normal tissues and that it was significantly correlated with a poor prognosis inovarian cancer patients." (PMID 36484005, 2022). "Following Elesclomol treatment of ovarian cancer cells, there was a notable increase in mitochondrial reactive oxygen species (ROS), a significant accumulation of the copper death marker protein DLAT, and a marked decrease in the lipoic acid synthesis-related protein FDX1." (PMID 41516324, 2025).
ovarian carcinoma (continued). "In conclusion, our study indicates that the detection of FDX1, DLAT, YY1 levels in the peripheral blood exosomes of patients with ovarian cancer can be used to quickly, accurately, and effectively predict the progress and prognosis of patients with ovarian cancer." (PMID 36484005, 2022).
atherosclerosis (6 papers, 2023 to 2025). A disease characterized by the build-up of fatty material and calcium deposition in the arterial wall resulting in partial or complete occlusion of the arterial lumen. "ApoE−/− mice exhibit significantly elevated lipid levels and atherosclerosis indices, with noticeable thickening of the aorta, lipid accumulation, and collagen fiber proliferation, which are associated with reduced expression of FDX1, LA, LIAS, and aconitase 2 (ACO2)." (PMID 39519014, 2024). "In early-stage atherosclerosis, genes such as ATP7A, GLS, DLD, ATP7B, and PDHA1 are highly expressed, whereas in later stages, the expression levels of FDX1, CDKN2A, SLC31A1, and MTF1 increase." (PMID 39519014, 2024). "In GSE132561, GSE28829, and GSE120521, the ROC curves of FDX1, GLS, and SLC31A1 also verified that both had a high value for classification of the atherosclerosis stage." (PMID 37442861, 2023). "In the training dataset GSE97210, SLC31A1, ATP7A, SLC31A2, UBE2D1, CP and FDX1 were highly expressed while LOXL2, COA6 and SOD1 were lowly expressed in the atherosclerosis group as showed in the bar charts." (PMID 37324184, 2023). "Furthermore, cuproptosis-related genes ferredoxin 1 (FDX1), solute carrier family 31 member 1 (SLC31A1), and glutaminase (GLS) are crucial in the onset and advancement of atherosclerosis." (PMID 40861271, 2025). "In our study, the different expressions of FDX1 in the two validation sets were inconsistent with those in the training set GSE97210, implying that FDX1 may not be an important factor involved in atherosclerosis." (PMID 37324184, 2023).
cervical cancer (6 papers, 2023 to 2025). A primary or metastatic malignant neoplasm involving the cervix. "The curcumin analog PBPD induces cuproptosis and endoplasmic reticulum stress in cervical cancer cells via the Notch1/RBP-J/NRF2/FDX1 pathway." (PMID 40276654, 2025). "We confirmed that the exogenous copper ionophore ES successfully induces cuproptosis in cervical cancer cells, as evidenced by downregulation of the key protein FDX1 and upregulation of HSP70." (PMID 41431124, 2025). "Compared with that in other cervical cancer cell lines, such as Caski and C33A cells, the expression of FDX1 in HeLa and SiHa cells is greater, which means that cuproptosis is more likely to occur." (PMID 39198750, 2024). "To investigate the relationship between angiogenesis and cuproptosis in cervical cancer, we identified two types of cells, FDX1 + tumor/epithelial cells and VEGFA + tumor/epithelial cells, and conducted cell-cell communication analysis." (PMID 38200479, 2024). "Therefore, we additionally detected differences in expression at the cellular level via qRT–PCR, and the experimental results showed low expression of FDX1 in a cervical cancer cell line, which was in accordance with our expectation." (PMID 37400520, 2023).
cervical squamous cell carcinoma (6 papers, 2022 to 2023). A squamous cell carcinoma arising from the cervical epithelium. "In contrast, higher FDX1 expression lead to better prognosis in patients with cervical squamous cell carcinoma(CESC) and clear cell renal cell carcinoma (KIRC)." (PMID 36882769, 2023). "Analysis of OS by Cox regression indicated that high expression of FDX1 was associated with longer survival times in cervical squamous cell carcinoma and endocervical adenocarcinoma (CESC) and KIRC, but not in HNSC and LGG." (PMID 36210836, 2022). "The highest frequency of FDX1 alterations (>3%) was observed in cervical squamous cell carcinoma and endocervical adenocarcinoma (CESC), followed by nonseminomatous testicular tumor (NSGCT) and seminoma (SEMI)." (PMID 36226187, 2022). "While in bladder urothelial carcinoma (BLCA), cervical squamous cell carcinoma and endocervical adenocarcinoma (CESC), esophageal carcinoma (ESCA), liver hepatocellular carcinoma (LIHC), and sarcoma (SARC), FDX1 showed no significant expression difference compared to normal tissues." (PMID 36605188, 2022).
testicular germ cell tumor (6 papers, 2022 to 2025). A germ cell tumor arising from the testis. "Our results illustrated that FDX1 expression was positively correlated with YTHDF2 and TRMT10C expression in most cancers, except LIHC and testicular germ cell tumors (TGCT)." (PMID 36210836, 2022).
uterine corpus endometrial carcinoma (6 papers, 2022 to 2025). A endometrial carcinoma (disease) that involves the body of uterus. "Furthermore, FDX1 expression is linked to specific immune subtypes in ACC, BRCA, KIRP, KIRC, LIHC, LGG, PRAD (prostate adenocarcinoma), SARC, STAD, THCA, and UCEC (uterine corpus endometrial carcinoma)." (PMID 38802900, 2024). "The results showed that FDX1 expression may be associated with specific different immune subtypes in ACC, BRCA, KIRP, KIRC, LIHC, LGG, PRAD (prostate adenocarcinoma), SARC, STAD, THCA and UCEC (uterine corpus endometrial carcinoma)." (PMID 37193786, 2023).
adrenocortical carcinoma (5 papers, 2022 to 2023). "Furthermore, OS by KM analysis revealed that FDX1 was a risk factor for patients with adrenocortical carcinoma (ACC), HNSC, LGG, and pancreatic adenocarcinoma (PAAD) and was a protective factor for patients with COAD, KIRC, and SKCM." (PMID 36210836, 2022). "Additionally, patients with higher FDX1 expression had poorer OS in ACC (adrenocortical carcinoma) (n = 38, HR = 2.2, P = 0.05)." (PMID 37193786, 2023). "We also discovered that cuproptosis-associated genes including FDX1, LIAS, PDHA1, MTF1, CDKN2A had significant overall survival (p < 0.05), which indicated that cuproptosis-associated genes could be prognosis factors in Adrenocortical carcinoma (ACC)." (PMID 36105090, 2022).
bladder cancer (5 papers, 2022 to 2024). "FDX1 can mediate lipid acylation of proteins to regulate cuproptosis, researches have discovered that FDX1 is also relevant to the regulation of multiple tumors, such as FDX1 can promote the cell viability of bladder cancer and prostate cancer." (PMID 38114959, 2023).
colon cancer (5 papers, 2023 to 2025). "For example, FDX1 expression was associated with quiescence and inflammation but negatively correlated with invasion in colon cancer." (PMID 37190215, 2023). "have demonstrated that the knockdown of FDX1 in human colon cancer cells significantly increased intracellular cholesterol levels." (PMID 40119652, 2025). "In this study, bioinformatics methods were used to analyze the expression level of FDX1 and its related genes, differentially expressed genes and their functions in colon cancer." (PMID 36173462, 2023). "Colon cancer is also enriched in copper ions and displayed cuproptosis, mediated by FDX1." (PMID 38658965, 2024). "In summary, we analyzed the expression of FDX1 in colon cancer by bioinformatics methods." (PMID 36173462, 2023). "Immunohistochemical results in HPA database showed that FDX1 was expressed in mucosa epithelium, lamina propria and submucosa of normal colon tissue, but no obvious expression was observed in colon cancer tissue." (PMID 36173462, 2023).
renal carcinoma (5 papers, 2022 to 2024). A carcinoma arising from the epithelium of the renal parenchyma or the renal pelvis. "Cuproptosis-related FDX1 expression and modification levels vary in renal carcinoma, which is associated with tumor cells’ function, immune regulation and prognosis." (PMID 38114959, 2023). "Moreover, we found the level of FDX1 in renal carcinoma and seminoma was lower than that in normal tissues." (PMID 35991547, 2022).
sarcoma (5 papers, 2022 to 2024). A usually aggressive malignant neoplasm of the soft tissue or bone. "Nevertheless, Fdx1+/- +/- exhibited a higher incidence of adenocarcinomas and sarcomas compared to WT mice." (PMID 38251655, 2024). "Nevertheless, like Fdxr+/- +/-, Fdx1+/- +/- showed significantly higher incidences of adenocarcinomas and sarcomas as compared to WT mice." (PMID 38251655, 2024). "Additionally, the results showed that FDX1 mRNA expression level was significantly higher in DLBC (lymphoid neoplasm diffuse large B-cell lymphoma) and THYM (thymoma) except SARC (sarcoma)." (PMID 37193786, 2023).
acute myeloid leukemia (4 papers, 2022 to 2023). Acute myeloid leukemia (AML) is a group of neoplasms arising from precursor cells committed to the myeloid cell-line differentiation. "In contrast, FDX1 expression was negatively correlated with CD40 expression in ACC, COAD, ESCA, KICH, KIRC, KIRP, acute myeloid leukemia (LAML), PRAD, STAD, and THCA, but was positively related to this gene expression in the other six cancers." (PMID 36210836, 2022). "There is a negative relationship between FDX1 expression and ICP genes in ACC, DLBC, LAML (acute myeloid leukemia), LIHC, THCA and THYM, which suggests that high FDX1 expression may predict unsatisfactory immunotherapy results when targeting these genes." (PMID 37193786, 2023).
Cerebral ischemia (4 papers, 2023 to 2025). Restriction of arterial blood supply to the brain associated with insufficient oxygenation to support the metabolic requirements of the tissue. "Disulfiram (DSF) has been shown to protect mitochondrial integrity and improve outcomes in cerebral ischemia in mice by downregulating FDX1 to regulate Cu homeostasis, inhibiting the HSP70/TLR4/NLRP3 inflammatory pathway, and reducing oxidative stress." (PMID 40951398, 2025). "Paradoxically, Cu2+ chelation using disulfiram (DSF) suppresses FDX1-mediated cuproptosis pathways, attenuating NF-κB activation and preserving BBB integrity during cerebral ischemia." (PMID 40951398, 2025). "Eight hub genes (FDX1, LIPT1, LIAS, DLD, PDHA1, DLAT, PDHB, and GLS) were identified as potential core targets of cerebral ischemia." (PMID 39360273, 2024).
pancreatic cancer (4 papers, 2022 to 2025). "TSF@ES‐Cu NPs transport copper ions into pancreatic cancer cells to produce rich ROS, destroy copper homeostasis of cells, down‐regulate FDX1 protein level, and induce DLAT protein aggregation, thus leading to cuproptosis of cells." (PMID 40091480, 2025). "Knocking down FDX1, a crucial protein in cuproptosis, was found to partially reverse the cell death induced by EB in this study, indirectly confirming that EB promotes pancreatic cancer cell death by triggering cuproptosis." (PMID 39100694, 2024). "The results showed that DLAT, FDX1, and LIAS were significantly correlated with DFI in pancreatic cancer patients, and DLAT was significantly correlated with DFI, DSS, OS, and PFS of pancreatic cancer." (PMID 36117848, 2022).
prostate carcinoma (4 papers, 2022 to 2024). A carcinoma that arises from epithelial cells of the prostate gland. "Secondly, although we proved that elesclomol decreased the cell survival of prostate cancer cells by targeting FDX1, the underlying regulatory mechanisms requires more investigation." (PMID 38671021, 2024). "Finally, an in vitro experiment showed that elesclomol, a cuproptosis inducer, targets ferredoxin 1 and suppress cell viability in prostate cancer cells." (PMID 38671021, 2024). "Finally, the effect of the cuproptosis-key gene FDX1 on prostate cancer cells were investigated through an in vitro experiment." (PMID 38671021, 2024). "Notably, elesclomol decreased cell survival in prostate cancer cells by targeting FDX1." (PMID 38671021, 2024).
cerebral infarction (3 papers, 2024). An ischemic condition of the brain, producing a persistent focal neurological deficit in the area of distribution of the cerebral arteries. "We found that DSF reduced the cerebral infarction volume, regulated the expression of cuproptosis-related proteins, and modulated copper content through down regulation of FDX1 expression." (PMID 38956251, 2024).
colitis (3 papers, 2022 to 2025). Inflammation of the colon. "Compared with DSS-induced colitis mice, PA treatment significantly reduced the loss of FDX1 and LIAS and significantly increased the level of protein lipoylation." (PMID 40969742, 2025). "Our study is the first to demonstrate the accumulation of copper in the colonic mucosa, resulting in the loss of Fe-S cluster-containing proteins FDX1 and LIAS and a reduction in DLAT oligomerization leading to cuproptosis in DSS-induced colitis mice." (PMID 40969742, 2025). "PA inhibited cuproptosis in the intestinal barrier of mice with colitis by reducing excess copper levels and DLAT oligomerization, as well as rescuing the loss of FDX1 and LIAS." (PMID 40969742, 2025). "We demonstrated that PA effectively inhibited cuproptosis in the colonic mucosa of colitis mice, as shown by the reduction in abnormally elevated copper levels in the colonic mucosa, restoration of FDX1, LIAS, and protein lipoylation levels, and decreased DLAT oligomerization." (PMID 40969742, 2025). "In this study, we observed that the transcription and protein expression of FDX1 and LIAS were significantly decreased in the colonic mucosa of patients with active UC with Mayo endoscopic scores ≥2 and in mice with DSS-induced colitis." (PMID 40969742, 2025). "Notably, when FDX1, LIPT1, and SLC25A3 are considered as potential drug targets, there is a concerning likelihood that they may precipitate an accelerated onset of colitis and depression." (PMID 40149491, 2025).